CXCL9 (C-X-C motif chemokine ligand 9)
Diseases named in the same sentence as CXCL9 in open-access papers (continued):
Sharing a sentence is not in itself a finding about the gene and the disease.
cancer (continued). "Cancer cells modulate the expression and secretion of several anti-proliferative molecules on DBMSCs, including, CD40LG, CXCL9, IL9R, IL-15, TNFSF13B, IL-9, IL-17, and CXCL1." (PMID 39768220, 2024). "Altogether, the data suggest that low C5aR is beneficial for the upregulation of CXCL9 and infiltration of CD8+ T cells in the TME, thus leading to a better survival in cancer patients." (PMID 38098230, 2024). "Seven chemokines (CCL18, CCL8, CXCL9, CXCL10, CXCL11, CCL26, and CCL7) showed positive relations in more than 25 cancer types." (PMID 38655053, 2024). "The main sources of its ligands, CXCL9, CXCL10, and CXCL11, are macrophages, endothelial cells, fibroblasts, and cancer cells." (PMID 39596815, 2024). "Higher CXCL9 and lower SPP1 expression was recently found to be correlated with a macrophage prognostic score in cancer patients." (PMID 38187708, 2024). "Among chemokines, especially CCL4, CCL5, CCL8, CXCL9, CXCL10 and CXCL11 were markedly positive correlated with LAMP3 expression in most cancers." (PMID 38146591, 2024). "We found that high expression of C5aR is observed in a number of tumors, including OC, and that C5aR expression strongly and negatively correlates with the levels of CXCL9 and CD8+ T cells in cancer patients." (PMID 38098230, 2024). "Another recently published study using imaging-based deep learning showed that CXCL9-mediated intratumoral clustering of cDC1s and CD8+ T cells is protective against cancer via increased antigen presentation and activation." (PMID 38786066, 2024). "QUE’s anti-inflammatory properties were also confirmed by the potent downregulation of pro-inflammatory chemokines, in particular the CXCR3 ligands CXCL9, CXCL10, and CXCL11, which are important players in chronic liver diseases, inflammation, and cancer." (PMID 37755981, 2023). "Two discovery pan-cancer datasets were used to examine the 4-chemokine signature (CCL4, CCL5, CXCL9, CXCL10; herein referred to as c-Score) as a predictive biomarker for T cell-inflammation and ICI treatment outcomes across different solid tumor types." (PMID 37558751, 2023). "IFN-γ promotes migration of immune cells to TME by transcriptionally regulating the expression and secretion of CXCL9, CXCL10 and CXCL11 and their cognate receptor CXCR3 in T cells, NK cells, monocytes, DCs and cancer cells." (PMID 37646041, 2023). "The c-Score, derived from expression of CCL4, CCL5, CXCL9, and CXCL10, identified subpopulations of tumors across cancer types with hallmarks of T cell-inflammation." (PMID 37558751, 2023). "C-X-C motif chemokine ligand 9 (CXCL9), which is involved in the pathological processes of various human cancers, has become a hot topic in recent years." (PMID 37644593, 2023). "Specifically, chemokines such as CXCL9, CXCL10, and CXCL11 and chemokine receptors such as CXCR5, CCR4, CCR8, and CCR1 were positively correlated with IGF2BP3 expression in various cancer types." (PMID 36761737, 2023). "Reports have asserted that the CXCL9, CXCL10, and CXCL11 axes are important for immune activation in cancer therapy." (PMID 37048082, 2023). "qPCR was performed for the treated murine 4T1, LLC, and CT26 cancer cell lines, and the data showed that the total expression levels of CCL5, CXCL9, and CXCL10 were significantly increased after tucidinostat treatment." (PMID 36352411, 2022). "Previous studies have found that when cancer cells reduce CCL5 production, CXCL9 expression also decreased." (PMID 35145917, 2022). "CXCL10, CXCL9, CXCL11/CXCR3 is an important axis for immune activation, which is necessary for developing novel cancer therapy." (PMID 36685901, 2022). "In order to precisely describe what chemokine is involved in T-cell homing, a transcriptomic approach, conducted in seven types of human cancers, proposed that CCL5 and CXCL9 expression is correlated with CD8A expression in the tumors." (PMID 36429101, 2022).
cancer (continued). "Specifically, we found that DAAM2 was positively correlated with the expression of critical immunomodulators, such as CCL5, CXCL9, and CXCL10, as well as the activities of the cancer-immunity cycle." (PMID 35281277, 2022). "Among them, CXCL9, CXCL10, and CXCL11 have been reported to promote cancer cell proliferation by combining with CXCR3A." (PMID 35992864, 2022). "We found the influx of NK and Th1 cells to the BM within cancer lesions to be dependent on the chemokine receptor CXCR3, which is expressed on NK cells and T cells, and on its ligand CXCL9, which is induced by IFN-γ." (PMID 35503658, 2022). "ANK2-MT LUAD was characterized by high expression of chemokines (CXCL9, CXCL10, CXCL11, and CXCR3) involved in the recruitment of anti-cancer immune cells." (PMID 36539782, 2022). "The differences between CXCL9 and CXCL10 in their biological functions, possibly through biased signaling, and their possible relevance to cancer immunotherapy have been discussed." (PMID 36479091, 2022). "We observed that immunostimulatory chemokines such as CXCL9, CXCL10, CXCL11, CCL4, and CCL5 were consistently down‐regulated for the tumors with high Hh activity across the 14 cancer types." (PMID 34841742, 2022). "The current findings showed that the expressions of multiple immune-related genes, including CXCL9, CXCL10, GZMB, and PDCD1LG2, were upregulated in cancer with high TME scores." (PMID 35242245, 2022). "Both CXCL9 and CXCL10 are chemokines secreted by monocytes, endothelial cells, fibroblasts and cancer cells in response to stimulation by IFN-γ." (PMID 36605208, 2022). "Therefore, CXCL9 may represent a new strategy for improving the efficacy of cancer immunotherapy." (PMID 36566226, 2022). "Pro-tumor chemokines, such as CXCL8, CXCL9, CXCL10, and CXCL11, can promote cancer cell proliferation and metastasis, and our results revealed that NEIL3 expression was positively correlated with them." (PMID 36612106, 2022). "The CCL4/CCR5 axis, CXCL9/CXCR3-axis, and CXCL13/CXCR5-axis have previously been shown to promote cancer progression and metastasis." (PMID 36163179, 2022). "It is well established that the IFN-γ signaling pathway regulates CXCL9 and CXCL10 expression in cancer cells." (PMID 36284313, 2022). "Simultaneous reduction of CXCR3, CXCL9, and/or CXCL10 expression suppresses cancer metastasis rates in melanoma, CRC,310 and breast cancer models." (PMID 35702353, 2022). "CXCL9, CXCL10, CXCL11, CXC12, CXCL13, and CXCL14 expression in the tissue adjacent to carcinoma was significantly different." (PMID 35181719, 2022). "Accordingly, we observed increased expression of IFNG-related genes in the CD8HIGH HPV+ subset, e.g., CCL5, CXCL9/13, CXCR6, and HLA-DRA, which contribute to a pan-cancer signature suggested to predict an optimum response to anti-PD1 immune checkpoint-therapy." (PMID 34771506, 2021). "Specifically, we discovered that IFITM3 was positively correlated with the expression of critical immunomodulators, such as CCL5, CXCL9, and CXCL10, as well as the activities of the cancer-immunity cycle." (PMID 34456915, 2021). "Based on the multivariate Cox proportional hazards model, levels of CXCL9 and CXCL11 remained independent prognosticators for overall survival after controlling for significant covariates such as patient age and cancer stage from the univariate Cox model." (PMID 34501934, 2021). "Regarding animal preclinical studies, as CXCL9 and CXCL10 mostly affect anti-cancer immunity the immunocompetent models are favorable." (PMID 34944943, 2021). "The chemokines CXCL9 and CXCL10, secreted upon exposure to zymosan or yeast-b and zymosan, respectively, are produced by monocytes, macrophages and cancer cells in response to IFN-y." (PMID 32860527, 2021). "Since CXCL9 and CCL3 are IFN-γ-related chemokines, here we focused on studying the anti-cancer effects of IFN-γ and TNF-α." (PMID 33175182, 2021).
cancer (continued). "A recent study showed that overexpression of CXCL5, CXCL9, and CXCL10 improved the immune function of cancer patients." (PMID 33323542, 2020). "The CXCL9, -10, -11/CXCR3 axis is involved in inflammatory responses, leukocyte trafficking, adaptive resistance, hematopoiesis, cancer cell transfer and angiogenesis." (PMID 33585219, 2020). "The CXCL9/CXCR3 axis regulates immune cell migration, differentiation, and activation and is therefore an important target for cancer therapy." (PMID 31126321, 2019). "We observed a high correlation between CD8+ T cell fractions and the expression of CXCL9 chemokine and chemokine receptor CXCR3 and, for some cancer types, with CXCL10 expression." (PMID 31126321, 2019). "M1 macrophages produce CXCL9 and CXCL10 and exert an anti-tumoral activity, while M2 macrophages sustain cancer growth." (PMID 30319638, 2018). "The IFN-γ/CXCL9, CXCL-10, CXCL-11/CXCR3 axis can be a double-edged sword in cancer, promoting an anti-tumor effect but also increasing the capability of cancer cell proliferation, angiogenesis and metastasis." (PMID 30631766, 2018). "Other models propose blockade of immune cell homing to cancer tissue by barrier molecules, chemo-inhibitory mechanisms, and by epigenetic silencing of chemokines (CCL5, CXCL9, and CXCL10), Th1 signaling molecules and antigen processing machinery components." (PMID 29871670, 2018). "And CD133+ cancer cells were reported to be related with the chemokine CCL5, so we also attempted to combine CXCL9 with the CD133+ cancer cells." (PMID 26883105, 2016). "However, in the section discussing “CXCL9 in cancer therapy” in this review, all the research conducted so far has suggested that high expression level of CXCL9 might be an important target for anti‐cancer therapies." (PMID 27726306, 2016). "Importantly, the C-X-C motif chemokine ligands CXCL9, CXCL10, and CXCL11 were significantly up-regulated in patients with high MOTIscores in both cancer types, suggesting the presence and activation of immune cells in these tumors." (PMID 41463470, 2025). "Differential expressions of CXCL9 and SPP1 were observed in a variety of cancers." (PMID 40230843, 2025). "Furthermore, IFN-γ regulates the expression and secretion of CXCL9, CXCL10, and CXCL11, along with their cognate receptor CXCR3 in various immune cells such as T cells, NK cells, monocytes, DCs, and cancer cells." (PMID 40040705, 2025). "CXCL9 and SPP1 already have established and arguably opposing roles in cancer biology." (PMID 40936719, 2025). "Other cell subtypes, including cancer-associated fibroblasts, natural killer (NK), NKT cells, neutrophils (Neu), and eosinophils, showed no or weak correlations with CXCL9/10 expression in LUAD and LUSC." (PMID 38518770, 2024). "CXCL9 is mainly produced by macrophages and DC, particularly CD106+ DC, whereas CXCL10 is mainly expressed by effector T cells and, in a wide range of tumors, by the cancer cells themselves." (PMID 39474427, 2024). "Our data suggest a potential use of CXCL9-Fc and/or CXCL10-Fc for cancer immunotherapy." (PMID 39474427, 2024). "The function of the CXCL9, -10, -11/CXCR3 axis in response to IFN-γ is mainly divided into two directions: paracrine signaling for immune activation and autocrine signaling for cancer cell proliferation and metastasis." (PMID 38143766, 2023). "However, only the functional roles of intratumoral CXCL9 and CXCL10 have been investigated phenotypically, with findings indicating that they contribute to cancer proliferation and migration." (PMID 38104126, 2023). "More importantly, the expression of PIK3R4 in DLBCL was correlated with the immune cell content in the cancer microenvironment, CD8(+) T-cell and neutrophil infiltration and the levels of several immune checkpoint molecules, including BTN3A2, BTN3A1, PRF1, CXCL9, PDCD1, and TIGIT." (PMID 37670973, 2023).
cancer (continued). "To examine whether MC1R represses Cxcl9/10/11 expression in transplanted B16F10-dCas9 tumors in vivo, we performed RNA-seq of isolated cancer cells from B16F10-dCas9 tumors expressing the Mc1r sgRNA versus the NTC sgRNA." (PMID 37714844, 2023). "Furthermore, three pairs of CXCL gene-immune cell interactions (CXCL13-CD8+ T cells, CXCL9/10-M1 cells, CXCL1/2/3/8-neutrophils) were identified through single-cell and pan-cancer analysis." (PMID 37540227, 2023). "In contrast, FMRP‐KO cancer cells could recruit CCR5+ and CXCR4+ CD8 T cells to indirectly kill cancer cells by promoting M1 macrophages to secrete proinflammatory chemokines CCL5, CXCL9, and CXCL10." (PMID 36968189, 2023). "While downregulated in the ID subgroup, B, M, and lesser T cell subgroups showed upregulated signaling of several chemokines (CXCL9/10/11, CCL3/13/18) to their cognate receptors on T and myeloid cell subsets, suggesting that cancer-cell-secreted chemokine gradients contribute to immune infiltration." (PMID 36368318, 2022). "For example, CXCL9, CXLC10, and CXCL11/CXCR3 has two main functions: it activates the immune response through the paracrine pathway and promotes the proliferation and metastasis of cancer cells through the autocrine pathway." (PMID 35992864, 2022). "Consequently, CXCL9 and CXCL10 promote lymphocyte infiltration into HCC and thus influence cancer immunology." (PMID 35897689, 2022). "This approach also allowed to integrate many lowly expressed genes oftentimes not well detected in single-cell data such as HOX9A and CXCL9 which are important in cancer progression and T cell recruitment, respectively." (PMID 36550535, 2022). "Therefore, CXCL9, CXCL10, and the CXCL11/CXCR3 axis have been regarded as potential cancer immune therapy targets." (PMID 35935945, 2022). "In addition, correlative studies in clinical trials can mechanistically explore the role of eosinophils in cancer immunotherapy by measuring baseline and on-treatment chemokines, such as CCL5/CXCL9/CXCL10/CCL11." (PMID 35954493, 2022). "Assessment of genes most upregulated within NHS–rmIL-12–treated carcinoma revealed increased expression of IFN-γ–responsive genes involved in antigen presentation, including B2m, H2-A, Cd74, the immune checkpoint Cd274, and the T lymphocyte chemokine Cxcl9." (PMID 35260537, 2022). "Stabilized CXCL9 and CXCL10 are likely to be good candidates for immunotherapy of cancer diseases." (PMID 34944943, 2021). "To further identify the potential soluble factors from MPE-Mφ-derived M1 macrophages might inhibit cancer cell growth, we performed experiments to examine the effects of M1-related cytokines (TNF-α, CXCL9, IFN-γ, or CCL3) on A549 cell proliferation." (PMID 33175182, 2021). "However, investigations have shown that the CXCL9-10-11/CXCR3 axis is able to contribute to the proliferation and metastasis of cancer cells." (PMID 34335758, 2021). "To address whether both CXCL9 and CXCL10 contribute to oncosphere formation and lung metastasis, we overexpressed the genes individually in MDA or SUM cancer cells." (PMID 32198421, 2020). "This CXCL9/10/11-CXCR3 axis activation can lead to upregulated expression of the immunosuppressor programmed death-ligand 1 (PD-L1) by activating the STAT and PI3K-Akt signaling pathways that play an important role in cancer treatment." (PMID 33304345, 2020). "Also, the transcriptional expressions of CXCLs family members were correlated with patients' individual cancer stages and nodal metastasis status, especially for CXCL2, CXCL3, CXCL4, CXCL7, CXCL9, CXCL10, CXCL11, and CXCL12." (PMID 32963527, 2020). "Using cancer-related pathway probes, we showed that STAT3 inhibited the expression of several IFN response genes in GICs, such as the chemokines CXCL9, CXCL10 and CXCL11, which is consistent with the finding that STAT3 can inhibit the expression of IFN response genes." (PMID 29774125, 2018).
cancer (continued). "As we found levels of the cytokines CCL5, CXCL9, CXCL10, and IL16 to indicate high CTL score across multiple cancers, we hypothesized that ATM in its role as a signal transducer may be promoting the transcription of these cytokines." (PMID 29615613, 2018). "Furthermore, targeting CXCL9 and TRANCE levels could enhance the effectiveness of existing cancer immunotherapies." (PMID 40489865, 2025). "Notably, chemokines like CXCL9, CXCL10, and CXCL11 are primarily produced by a variety of cell types, including monocytes, endothelial cells, fibroblasts, and cancer cells, in response to IFN-γ, and this response is further amplified by TNF-α, highlighting their role as pro-inflammatory cytokines." (PMID 40227454, 2025). "The presence of transient PD-L1+/CXCL9+/CXCL10+ myeloid clusters at sites that later develop tumors suggests that immune organization itself may serve as an early biomarker—and potentially a therapeutic target—for cancer interception." (PMID 41279770, 2025). "In parallel with considerable overproduction of other pro-inflammatory modulators, such as TNFα, IL-2, IL-6, MIG (CXCL9), MIP-1β (CCL4) and MIP-2 (CXCL2), we also detected a significantly lower secretion of IL-10 by tILC2s that contradicted the conventional ILC2 role in cancer." (PMID 38524132, 2024). "Firstly, bioinformatics analysis of the public cancer database, including the Cancer Genome Atlas / the Genotype-Tissue Expression project (TCGA+ GTEx, n=552) and Gene Expression Omnibus (GEO): GSE63678 (n=7), were utilized for the CXCL9 expression-related analysis in UCEC." (PMID 36845675, 2023). "Enhancement of paracrine CXCR3 ligands (CXCL9, CXCL-10, and CXCL-11) in the tumor microenvironment and deactivation of CXCR3 expression on cancer cells could be antitumorigenic by recruiting activated natural killer cells and T lymphocytes with potent antitumor effects in various lung cancer models." (PMID 36164329, 2022). "However, we discovered that ATS may have an immunosuppressive effect by downregulating the expression of key chemokines such as CXCL9, CXCL10, and CXCR3, and therefore decreasing the cancer immunity." (PMID 36302799, 2022). "However, we found that Siglec15 may exert an immunosuppressive function by comprehensively downregulating the expression of critical immunomodulators such as CXCL9, CXCL10, and CXCR3, and subsequently downregulating the activities of the cancer-immunity cycle." (PMID 33537076, 2021). "Interferon-γ (IFN-γ) is the major inducer of three CXCR3 ligands, monokine induced by IFN-γ (MIG)/CXCL9, 10 kDa IFN-γ-induced protein (IP-10)/CXCL10 and IFN-inducible T cell α chemoattractant (I-TAC)/CXCL11 in mainly endothelial cells, monocytes, fibroblasts, and cancer cells." (PMID 34503058, 2021). "Finally, we discuss the possibility that CXCL9 and CXCL10 may differ in their biological function via biased signaling and its possible relevance to cancer immunotherapy." (PMID 32547545, 2020). "However, in mice injected with cancer cells overexpressing CXCL9/10, lung colonization was not affected by JNKi pretreatment." (PMID 32198421, 2020). "CXCL9, CXCL10, and CXCL11 (C-X-C motif chemokine ligand 9, 10, and 11, respectively) are chemokines that share functions as ligands of CCR3, stimulating antitumoral immunity, but they can also promote proliferation and metastasis in cancer cells in an autocrine pathway, as recently reviewed." (PMID 32117120, 2020). "Interestingly, in follicular lymphoma (FL), elevated levels of CXCL9 result in lower event-free survival after treatment with immunotherapy implying a potential negative role of this chemokine after cancer treatment." (PMID 31216755, 2019). "Notably, CXCL9, CXCL10, and IFNG had significantly higher expression levels in the higher-TMB subtype of at least 10 cancer types, while had significantly higher expression levels in the lower-TMB subtype of at most 4 cancer types." (PMID 30634925, 2019).